MMP2 (matrix metallopeptidase 2)
Diseases named in the same sentence as MMP2 in open-access papers (continued):
Sharing a sentence is not in itself a finding about the gene and the disease.
atherosclerosis (134 papers, 2011 to 2026). A disease characterized by the build-up of fatty material and calcium deposition in the arterial wall resulting in partial or complete occlusion of the arterial lumen. "First, there is only one study that focuses on association of MMP-2 gene polymorphisms with the occurrence of atherosclerosis and CAD." (PMID 37457745, 2023). "Another study analyzing atherosclerosis-associated biomarkers in T2DM females reported a decrease in MMP2 and MMP9 levels with an increase in GLP-1 and GLP-1R levels." (PMID 37686344, 2023). "It is known that MMP-2 plays a role in promoting atherosclerosis, since atherogenesis is reduced in MMP-2-deficient ApoE−/− mice." (PMID 34797846, 2021). "MMP-2 expression is associated with the induction of SMC hyperplasia during atherosclerosis and restenosis." (PMID 28924208, 2017). "Two SNPs of the MMP-2 gene (rs243865 and rs243866) were associated with atherosclerosis." (PMID 37457745, 2023). "In addition, two single nucleotide polymorphisms of the MMP-2 gene (rs243865 and rs243866) were significantly associated with the development of atherosclerosis." (PMID 37457745, 2023). "A previous animal study demonstrated that montelukast inhibited the development of atherosclerosis in association with decreased expression of MMP-2 and MMP-9, and another experimental study indicated that montelukast produced anti-atherogenic effects related to MCP-1 downregulation." (PMID 31263710, 2019). "This suggests that OLE might have additional (SAA-independent) beneficial effects on the MMP2-driven atherosclerosis-associated remodeling of the vascular wall." (PMID 31157238, 2019). "In addition, future studies can further screen for potential biomarkers closely associated with cardiovascular status, atherosclerosis progression, and aneurysm pathogenesis, such as the matrix metalloproteinase family (MMPs, including MMP-2, MMP-9), which mediate extracellular matrix remodeling." (PMID 40697999, 2025). "It was reported previously that MMP-2 was produced and released from the vascular SMCs after stimulation by a variety of the local substances strictly related to the clinical risk factors for the development of atherosclerosis, such as diabetes mellitus, hypertension, smoking, and ageing." (PMID 24151618, 2013). "Parallel analysis of SMA expression served as a biomarker for VSMCs, which predominantly express ETAR, whereas MMP-2 served as a biomarker for advanced atherosclerosis." (PMID 40076930, 2025). "MMP-2 is involved in multiple cardiovascular conditions such as aortic aneurysm formation, atherosclerosis, chronic thromboembolic pulmonary hypertension (CTEPH), and myocardial fibrosis." (PMID 39769454, 2024). "In atherosclerosis, MMP-2 degrades ECM components within the arterial walls, contributing to plaque destabilization and rupture." (PMID 39769454, 2024). "PDGF-CC participates in the formation of atherosclerosis by triggering MMP-2 and MMP-9 expression and monocyte migration and invasion." (PMID 38273388, 2024). "In cultured HAECs, we demonstrate that Oxy210 can inhibit the high baseline and TGF-β-induced expression of CCL-2 and MMP2, further supporting its potential utility in the context of vascular inflammation and atherosclerosis." (PMID 39404395, 2024). "MMP-2 in particular is known to promote atherosclerosis, and increased activity of MMPs has been shown to cause neointimal arterial lesions and smooth muscle cell migration." (PMID 37958625, 2023). "The current review aimed to identify the role of MMP-2 in atherosclerosis development among CAD patients." (PMID 37457745, 2023).
atherosclerosis (continued). "It has been reported that the expression of both MMP-9 and MMP-2 is increased in HFD-fed ApoE−/− mice with the development of atherosclerosis." (PMID 37998401, 2023). "The aim of this review was to determine the role of MMP-2 in atherosclerosis development in CAD patients." (PMID 37457745, 2023). "The secretion of MMP2, which promotes cell invasion and migration of vascular smooth muscle cells (VSMCs), influences the process of atherosclerosis." (PMID 36959823, 2023). "To conclude, this review has identified some studies that demonstrate the role of MMP-2 in atherosclerosis progression among patients with CAD." (PMID 37457745, 2023). "In the process of atherosclerosis (AS), MMP2 can degrade a variety of collagen and basement membrane components, lyse the collagen fibers of AS plaques, and reduce the thickness of the fibrous cap at the plaque." (PMID 37999247, 2023). "Other studies have shown that the involvement of MMPs in atherosclerosis leads to a reduction in atherosclerotic lesions when using double knockout animals for ApoE-⁄- and MMP-2-⁄-, MMP-8-⁄-, and MMP-9-⁄- and MMP-12-⁄-." (PMID 35269673, 2022). "Studies with patients with atherosclerosis also show MMP-2 as a marker of injury and mortality, which reinforces the effects observed by doxycycline in this study as promising for further studies." (PMID 35269673, 2022). "The increase in MMP-2 activity by gel zymography is shown in different models of atherosclerosis, which demonstrates that the rise in the activity of this gelatinase results in the progression of atherosclerotic lesions." (PMID 35269673, 2022). "Tissue relaxin-2 mRNA levels are inversely correlated with MMP-2 in mild atherosclerosis and positively correlated with eNOS in moderate atherosclerosis, which supports the beneficial effect of relaxin-2 in this pathology." (PMID 35887517, 2022). "In atherosclerosis, MMP2 and MMP9 are known to be overexpressed and act as key regulators of ECM remodeling." (PMID 35680971, 2022). "With a particular focus on atherosclerosis imaging, we highlight recent approaches to report on the activity of cathepsins (K and B), matrix metalloproteinases (MMP-2 and MMP-9), thrombin, heme oxygenase-1 (HO-1) and myeloperoxidase (MPO)." (PMID 34605500, 2021). "have highlighted a role of ginkgetin in improving atherosclerosis by reducing MMP-2 and MMP-9 and increasing levels of NO and NOS in thoracic aortas of rat52." (PMID 33854174, 2021). "The level of MMP-12, which can hydrolyze elastin and intercellular matrix proteins, as well as activating MMP-3 and MMP-2, was statistically significantly higher in the group of men with atherosclerosis—2.1 times compared to the control group." (PMID 34205079, 2021). "Both MMP-2 and MMP-9 are important members of the MMP family, and are also implicated with cell migration by medicating inflammatory cell infiltration in atherosclerosis." (PMID 32314783, 2020). "Meanwhile, by established an EC-SMC-MC co-culture system, the study showed that tanshinone IIA, an active ingredient of SL, exhibited significant efficacy against atherosclerosis and inhibited the inflammatory MMP-2 and NF-κB pathway." (PMID 32210797, 2020). "Two large meta-analyses have separately summarized the strength of the relationship between MMP-2, TIMP-1, and subclinical atherosclerosis in CKD patients or between MMPs and vascular risk, regardless of the level of kidney function." (PMID 31963569, 2020). "A study on atherosclerosis found that blocking the PDGF-PDGFR signaling pathway can reduce MMP-2 and MMP-9 expression in atherosclerotic plaques in mice." (PMID 31777578, 2019). "Matrix metalloproteinase-9 and MMP-2 are members of the MMP family that are closely related to the stability of atherosclerosis plaques." (PMID 30142970, 2018). "At the early stage of atherosclerosis, activity of MMP-2 can degrade the basal membrane of ECs, and decrease the defense of ECs, and further to lead to LDL to tunica intima." (PMID 30142970, 2018).
atherosclerosis (continued). "The severity of atherosclerosis in MMP-2 and ApoE double gene knockout mice has been reported to be less than that in ApoE single gene knockout mice." (PMID 28450836, 2017). "It is also possible that the higher MMP-2 expression measured simply reflected the greater atherosclerosis in the mice receiving RDN although the fact other atherosclerosis-associated genes were not different supports a causative association." (PMID 28450836, 2017). "Levels of proteins (osteoprotegerin, osteopontin, osteocalcin, matrix γ-carboxyglutamic acid protein, fetuin A, MMP-2, MMP-9, TIMP-1, TIMP-2) and biochemical parameters were measured to analyse their influence on atherosclerosis risk in CKD patients." (PMID 26843213, 2016). "The association between MMP-2 and TIMP-1 with atherosclerosis was the most frequently assessed (four studies) with MMP-9 also assessed in three." (PMID 27042350, 2016). "cIMT was the main measure of subclinical atherosclerosis reported and MMP-2 and TIMP-1 were the most commonly assessed metalloproteinases." (PMID 27042350, 2016). "Detailed analysis of microparticles showed that the two principle gelatinases essential for atherosclerosis progression, MMP-2 and MMP-9, were discovered on the outer side of the microparticles membrane." (PMID 27066292, 2016). "In summary, our current results have showed that DEHP can be a potent inducer of atherosclerosis by increasing MMP-2 and MMP-9 expression at least through the regulations of p38 MAPK, ERK1/2, Akt, and NF-κB." (PMID 26690114, 2015). "MMP-2 contributes to the development of atherosclerosis and, activated MMP-2 has been observed in human carotid endarterectomy specimens." (PMID 25936371, 2015). "MiR-29b suppressed the proliferation and migration of SMCs and prevents atherosclerosis through the inhibition of their targets Mcl-1 and MMP2." (PMID 25664324, 2015). "Gelatinases A and B (MMP-2 and -9) are involved in the vascular remodelling that precedes the atherosclerosis development and also in its worse outcomes." (PMID 25114377, 2014). "Atherosclerosis is a process of chronic inflammation, and MMPs, specifically, MMP-2 and MMP-9, are the principal enzymes in extracellular matrix degradation essential for the invasion and migration of VSMCs." (PMID 24739942, 2014). "MMP-2 is able to degrade the extracellular matrix in atherosclerotic plaque and participates in the formation of atherosclerosis." (PMID 24319687, 2013). "Although vascular protective effects of rosiglitazone in some atherosclerosis models and cell culture are known, its effects on proinflammatory gelatinase A and B enzymes (MMP-2 and MMP-9) related to atherosclerotic process were not thoroughly understood." (PMID 22716287, 2012). "Unsupervised DEGs analysis of SMCs revealed increased expression in Abcb8ECKO of TGF-β-pathway genes such as Tgfb1, Tgfb2, Tgfb3, Mmp2 and Col1a1, inflammatory genes such as Ccl2 (encoding for MCP1) and Csf1 as well as atherosclerosis-associated genes including Egr1, Sqstm1, Irf1, Sox4 and Xylt1." (PMID 41252867, 2025). "Beyond SMA, we used MMP2 as a biomarker for advanced atherosclerosis." (PMID 40076930, 2025). "Similarly, during atherosclerosis, macrophage-derived ROS upregulate MMP2/9 to degrade COL-IV, promoting plaque rupture." (PMID 40646747, 2025). "This may be related to the increased inflammation and oxidative stress in hemodialysis patients, as serum MMP-2 is known as a marker of inflammation which is a key mechanistic pathway in the accelerated atherosclerosis in dialysis patients." (PMID 38765135, 2024). "SMAD3, TNF, MMP2, MMP9, CTGF, CD44 and AKT1 are associated with atherosclerosis." (PMID 37328880, 2023). "MMP-2 is widely distributed in endothelial cells, VSMCs, leukocytes, platelets, adventitia, and dermal fibroblasts, and is essential for the development of atherosclerosis." (PMID 37457745, 2023).
atherosclerosis (continued). "This review could increase our understanding on the role of MMPs, specifically MMP-2 in atherosclerosis development among CAD patients, which could help in early disease diagnosis and development of targeted therapy via the MMP-2 signaling pathway." (PMID 37457745, 2023). "In conclusion, MMP-2 plays a crucial role in the development of atherosclerosis among patients with CAD and could be a potential target for CAD therapy." (PMID 37457745, 2023). "By activating this pathway, MMP-2 stimulates oxLDL-induced VSMCs proliferation in atherosclerosis." (PMID 37457745, 2023). "The CA, CG, and TA haplotypes of the MMP-2 gene were significantly connected with atherosclerosis." (PMID 37457745, 2023). "Taken together, C. pneumoniae infection may promote VSMC migration and atherosclerosis development by increasing the level of mtROS through TLR2 to activate the JunB-Fra-1/MMP2 signaling pathway." (PMID 35493076, 2022). "Furthermore, in ApoE‐/‐ mice model of C. pneumoniae infection-induced atherosclerosis, the expressions of JunB, Fra-1 and MMP2 in VSMCs in atherosclerotic lesions were also increased compared with mock infected ApoE‐/‐ mice." (PMID 35493076, 2022). "Accordingly, reducing the level of mtROS to block C. pneumoniae infection-induced VSMC migration-related signal axis, JunB-Fra-1/MMP2 signal axis, may become a potential treatment target for C. pneumoniae infection-induced atherosclerosis." (PMID 35493076, 2022). "Therefore, in this study, lipid levels, SOD activity, ROS activity, VEGFA, and MMP-2 expression were measured in mice with CHD to assess the effect of EGCG on the formation as well as progression of atherosclerosis." (PMID 35919501, 2022). "Here, as compared with UIAs without AWE, a higher aneurysm wall remodeling ratio (14/20 in UIAs without AWE, and 14/14 in UIAs with AWE), severer inflammation (CD68 and MMP2) and larger atherosclerosis area could be found in UIAs with AWE." (PMID 35155635, 2022). "Whether TLR2/mtROS/JunB-Fra-1/MMP2 signal axis participates in C. pneumoniae infection-induced atherosclerosis development remains unknown." (PMID 35493076, 2022). "However, this research seeks to understand if treatment with doxycycline in an already-established model of atherosclerosis will have an antiatherogenic effect by modulating the activity and expression of MMP-2 and ROS." (PMID 35269673, 2022). "Additionally, MMP2 and MMP9 (also known as gelatinase A and gelatinase B, respectively) were found to be constitutively overexpressed in models of chronic VO as well as in models of atherosclerosis and cardiomyopathy." (PMID 32271823, 2020). "When the atherosclerosis endothelium is damaged, monocytes/macrophages and ECs secrete MMP-2." (PMID 30142970, 2018). "In this experimental model of atherosclerosis, we successfully prove and visualize overexpression of MMP-2 and MMP-9 in unstable upstream low oscillatory shear stress plaques as compared to the high laminar shear stress-induced downstream plaques and control carotids." (PMID 30304051, 2018). "Since the activation state of gelatinases seems to be of crucial importance for their function in atherosclerosis, we questioned whether the MMP‐2 and MMP‐9 produced by the SMC after co‐culture with MAC are secreted and have gelatinolytic activity." (PMID 29992758, 2018). "It is therefore possible that the upregulation of MMP-2 identified in mice receiving RDN may have promoted atherosclerosis within the aorta." (PMID 28450836, 2017). "Therefore, MMP2/9, is another group of key factors that intertwines amyloidosis, aging, hypertension and atherosclerosis." (PMID 29085385, 2017). "Moreover, in LDL receptor knockout mice, red wine was also able to reduce atherosclerosis lesions by inhibiting the production and activation of MMP-2." (PMID 27589705, 2016). "MMP-2 also contributes to the development of atherosclerosis." (PMID 28105926, 2016).
atherosclerosis (continued). "Thus, MIF gene interference stabilizes atherosclerosis plaque likely by inhibiting MMP-2 and MMP-9 expression, up-regulating TIMP-1 expression and decreasing the ratio of MMP-2/TIMP-1." (PMID 25661015, 2015). "Our results strongly suggest that DEHP may induce atherosclerosis development by increasing expression of MMP-2 and MMP-9 via p38 MAPK-, ERK1/2-, Akt-, and NF-κB-mediated pathways." (PMID 26690114, 2015). "MMP-2 expression in vascular smooth muscle cells (VSMC) has been linked to several pathological situations, particularly in atherosclerotic plaques, which suggesting a pathogenic role for MMP-2 in the progression of atherosclerosis." (PMID 26690114, 2015). "IL-1β, TNF-α, MCP-1 and MMP-2 can promote the progression of atherosclerosis." (PMID 24755612, 2014). "Indeed, our findings support that atherosclerosis development is accompanied by an increase in MMP-2, MMP-3, MMP-8, MMP-9, TIMP-1 and TIMP-2 levels." (PMID 25264981, 2014). "To investigate whether CCN3 is capable of regulating the inflammatory factors in atherosclerosis, we first analyzed the expression of MMP-2 and MMP-9 by ELISA." (PMID 24722330, 2014). "The expression levels of MMP-2 in the atherosclerotic plaques are significantly increased and affect the stability of plaque, which provides a new method for the screening and diagnosis of atherosclerosis." (PMID 24319687, 2013). "Additionally, MMP-2 and MMP-9 are linked to inflammatory responses (GO:0006954) and are highly expressed in chronic inflammatory conditions such as rheumatoid arthritis and atherosclerosis." (PMID 40868841, 2025). "Immunostaining showed a significant increase in Collagen I and MMP2 in the aorta of Abcb8ECKO mutants, corroborating the scRNAseq data and indicating that Abcb8 loss induces collagen synthesis and MMP-2 levels, both known to play a role in atherosclerosis plaque development." (PMID 41252867, 2025). "Indeed, MMP-2 was positively associated with carotid Intima-Media Thickness (cIMT) and abdominal aortic calcification, suggesting that an association between this MMP and subclinical atherosclerosis is plausible." (PMID 31963569, 2020). "Moreover, MMP-2 expression in VSMC is significantly increased in vulnerable regions of atherosclerotic plaques, suggesting a pathogenic role for MMP-2 in the progression of plaque rupture in hypertension-related atherosclerosis." (PMID 23950935, 2013). "In conclusion, we used dual-modality molecular imaging with an activatable MMP-2/9 probe and Raw-luc macrophages to characterize a new mouse model with two different types of atherosclerotic vascular disease: conventional lipogenic atherosclerosis and shear related mechanical atherosclerosis." (PMID 24069197, 2013). "Regarding cardiovascular pathology, MMP-2 and MMP-9, also known as gelatinase A and B, act as key contributors to the development of atherosclerosis, myocardial infarction (MI), HF, and coronary thrombosis." (PMID 40305314, 2025). "SGLT2 inhibitors inhibit atherosclerosis by normalizing the expression of inflammation-related genes such as TNF-α, IL-6, ICAM-1, MMP2, and MMP9." (PMID 40869372, 2025). "In a low-grade inflammation state, such as established atherosclerosis, E2 can destabilize atherosclerotic plaques by inducing molecules like MCP-1 and matrix metalloproteinases (specifically MMP-2 and MMP-9) in endothelial cells." (PMID 40564184, 2025). "MMP is a known contributor to atherosclerosis development; unstable CAD patients had significantly higher MMP2 levels and activity than stable CAD patients and healthy individuals." (PMID 39200916, 2024).